KDM1A (lysine demethylase 1A)
Description:
Histone demethylase that can demethylate both 'Lys-4' (H3K4me) and 'Lys-9' (H3K9me) of histone H3, thereby acting as a coactivator or a corepressor, depending on the context. Acts by oxidizing the substrate by FAD to generate the corresponding imine that is subsequently hydrolyzed. Acts as a corepressor by mediating demethylation of H3K4me, a specific tag for epigenetic transcriptional activation. Demethylates both mono- (H3K4me1) and di-methylated (H3K4me2). May play a role in the repression of neuronal genes. Alone, it is unable to demethylate H3K4me on nucleosomes and requires the presence of RCOR1/CoREST to achieve such activity. Also acts as a coactivator of androgen receptor (AR)-dependent transcription, by being recruited to AR target genes and mediating demethylation of H3K9me, a specific tag for epigenetic transcriptional repression. The presence of PRKCB in AR-containing complexes, which mediates phosphorylation of 'Thr-6' of histone H3 (H3T6ph), a specific tag that prevents demethylation H3K4me, prevents H3K4me demethylase activity of KDM1A. Demethylates and stabilizes the DNA methylase DNMT1. Demethylates methylated 'Lys-42' and methylated 'Lys-117' of SOX2. Required for gastrulation during embryogenesis. Component of a RCOR/GFI/KDM1A/HDAC complex that suppresses, via histone deacetylase (HDAC) recruitment, a number of genes implicated in multilineage blood cell development. Facilitates epithelial-to-mesenchymal transition by acting as an effector of SNAI1-mediated transcription repression of epithelial markers E-cadherin/CDH1, CDN7 and KRT8. Required for the maintenance of the silenced state of the SNAI1 target genes E-cadherin/CDH1 and CDN7. Required for the repression of GIPR expression. [Isoform 2]: Neuron-specific histone demethylase that demethylates mono- and dimethylated 'Lys-20' of histone H4 (H4K20me1 and H4K20me2), a chromatin repressive mark. This demethylation is crucial for the initiation and elongation of neuronal activity-regulated genes, required for spatial learning and memory (By similarity). Mediates H3K9me2 demethylation through cooperation with the supervillin protein (SVIL), and this H3K9 demethylase activity is essential for regulating gene expression during neuronal differentiation. [Isoform 4]: Neuron-specific histone demethylase that demethylates mono- and dimethylated 'Lys-20' of histone H4 (H4K20me1 and H4K20me2), a chromatin repressive mark. This demethylation is crucial for the initiation and elongation of neuronal activity-regulated genes, required for spatial learning and memory (By similarity). Mediates H3K9me2 demethylation through cooperation with the supervillin protein (SVIL), and this H3K9 demethylase activity is essential for regulating gene expression during neuronal differentiation.
Synonyms: AOF2; BHC110; KDM1; KIAA0601; LSD1; AIMAH3; CPRF
Tractability: Small molecule: a drug acting on it is in phase 2 or 3 trials; a structure with a bound ligand is known; a high-quality ligand is known; it has a high-quality binding pocket; it belongs to a druggable protein family. PROTAC: UniProt records ubiquitination sites on it; ubiquitination databases record sites on it; its protein half-life has been measured; a small molecule that binds it is known.
Target class: Lysine demethylase; Lysine-specific demethylase; Epigenetic regulator; Eraser
Chemical probes: CHEMBL3134375, GSK-LSD1 (high quality), PD080851, PD082909, PD085064, SP2509
Gene: Protein-coding gene on chromosome 1 (23,019,395 to 23,083,693, forward strand). Ensembl gene ENSG00000004487.
Subcellular location: Nucleus; Chromosome
Subcellular location (Human Protein Atlas): Nucleoplasm; Cytosol
Pathways (Reactome):
Signal Transduction: Activated PKN1 stimulates transcription of AR (androgen receptor) regulated genes KLK2 and KLK3; Estrogen-dependent gene expression; NR1H3 & NR1H2 regulate gene expression linked to cholesterol transport and efflux; Regulation of PTEN gene transcription
Chromatin organization: HDACs deacetylate histones; HDMs demethylate histones
Cell-Cell communication: Negative Regulation of CDH1 Gene Transcription
Disease: Potential therapeutics for SARS
Hemostasis: Factors involved in megakaryocyte development and platelet production
Gene Ontology:
Molecular function: chromatin binding; DNA-binding transcription factor binding; enzyme binding; FAD-dependent H3K4me/H3K4me3 demethylase activity; flavin adenine dinucleotide binding; histone demethylase activity; histone H3K4 demethylase activity; histone H3K9 demethylase activity; histone H3K9me/H3K9me2 demethylase activity; histone H4K20 demethylase activity; identical protein binding; MRF binding; nuclear androgen receptor binding; oxidoreductase activity; protein binding; protein demethylase activity; telomeric DNA binding; telomeric repeat-containing RNA binding; transcription coactivator activity; transcription corepressor activity; promoter-specific chromatin binding; RNA polymerase II-specific DNA-binding transcription factor binding; 2-oxoglutarate-dependent dioxygenase activity; histone H3K9me2/H3K9me3 demethylase activity; and 3 more
Biological process: cellular response to gamma radiation; cellular response to UV; DNA repair-dependent chromatin remodeling; negative regulation of transcription by RNA polymerase II; negative regulation of transcription initiation-coupled chromatin remodeling; positive regulation of epithelial to mesenchymal transition; positive regulation of neuroblast proliferation; positive regulation of protein ubiquitination; positive regulation of transcription by RNA polymerase II; regulation of double-strand break repair via homologous recombination; regulation of protein localization; regulation of transcription by RNA polymerase II; epigenetic regulation of gene expression; muscle cell development; negative regulation of DNA-templated transcription; positive regulation of cold-induced thermogenesis; positive regulation of neural precursor cell proliferation; positive regulation of stem cell proliferation; regulation of androgen receptor signaling pathway; granulocyte differentiation; neuron development; positive regulation of cell differentiation; and 6 more
Cellular component: chromatin; chromosome; chromosome, telomeric region; DNA repair complex; histone methyltransferase complex; nucleoplasm; nucleus; protein-containing complex; transcription repressor complex; transcription regulator complex
Genetic constraint (gnomAD): Loss-of-function variants: 30 observed, 63.78 expected, observed/expected ratio (o/e) 0.47, 90% interval 0.35 to 0.64. The upper end of that interval is the gene's LOEUF score, 0.64, which puts it in group 2 of 6, group 1 being the genes least tolerant of losing a copy. Missense variants: 507 observed, 801.23 expected, observed/expected ratio (o/e) 0.63, 90% interval 0.59 to 0.68. Synonymous variants: 299 observed, 298.1 expected, observed/expected ratio (o/e) 1, 90% interval 0.91 to 1.1.
Gene-disease validity (ClinGen):
ClinGen rates the evidence that KDM1A causes each of these diseases.
palatal anomalies-widely spaced teeth-facial dysmorphism-developmental delay syndrome (autosomal dominant): Definitive.
Homologues: Orthologues: chimpanzee KDM1A (99% identical), macaque KDM1A (99% identical), dog KDM1A (99% identical), rat Kdm1a (99% identical), pig KDM1A (98% identical), mouse Kdm1a (98% identical), rabbit KDM1A (93% identical), guinea pig KDM1A (92% identical), tropical clawed frog kdm1a (86% identical), zebrafish kdm1a (83% identical), Drosophila melanogaster Su(var)3-3 (51% identical), Caenorhabditis elegans lsd-1 (15% identical), and 1 more. Paralogues in human: KDM1B (27% identical), MAOA (13% identical), SMOX (13% identical), MAOB (13% identical), IL4I1 (12% identical), PAOX (12% identical), PPOX (7% identical).
Diseases named in the same sentence as KDM1A in open-access papers:
KDM1A is named in the same sentence as 307 diseases in open-access papers, as found by Europe PMC text mining. Sharing a sentence is not in itself a finding about the gene and the disease. The quoted sentences say what the papers report.
breast carcinoma (218 papers, 2010 to 2025). "KDM1A-driven HIF1A has been associated with aggressive behavior in breast cancer cells, and HIF1A was shown to enhance angiogenesis, cell migration, and colony formation in the Hif1αKA/KA knock-in mouse model." (PMID 39458030, 2024). "High KDM1A expression was associated with a decrease in the anticancer immune response in breast cancer." (PMID 33799951, 2021). "The result presented that the high expression of KDM1A was associated with better OS (p = 0.0068) but the reverse effect to RFS (p = 0.001) in patients with breast cancer." (PMID 34925656, 2021). "Subsequently, we surveyed the association of breast cancer subtype and the KDM1A alteration and found 5 of 7 cases with KDM1A alteration were luminal A type of breast cancer." (PMID 34925656, 2021). "In a previous study, expression of KDM1A in breast cancer was reported for its association with cytotoxic T cell chemokines and PD-L1 and was consistent with our results." (PMID 33799951, 2021). "KDM1A has also been found to interact with another breast cancer-associated lncRNA, steroid receptor RNA activator (SRA)." (PMID 29921310, 2018). "Furthermore, it has been shown that high KDM1A expression is associated with progression from ductal carcinoma in situ (DCIS) to invasive ductal carcinoma (IDC) in breast cancer." (PMID 33799951, 2021). "Our study demonstrated that high KDM1A expression is significantly associated with worse clinicopathological parameters in patients with breast cancer, with high KDM1A expression indicating a higher frequency of lymph node metastasis, higher histological grade, and more lymphatic invasion." (PMID 33799951, 2021). "Therefore, high KDM1A expression is associated with the growth of breast cancer cells and the effects of alisertib." (PMID 33799951, 2021). "Lysine-specific demethylase 1 (LSD1, also known as KDM1A) has been found to be highly expressed in neurocytoma, colon cancer, breast cancer and other tumor types, and high expression is associated with poor tumor prognosis." (PMID 38581529, 2024). "KDM1A has been found to be highly expressed in colon cancer, breast cancer, neurocytoma and other tumor types, and high expression is associated with poor tumor prognosis." (PMID 38581529, 2024). "The KDM1A (LSD1) inhibitor has been investigated as a therapeutic target in breast cancer because it has shown promising results in inhibiting the growth and invasion of cancer cells." (PMID 37108398, 2023). "Particularly, KDM1A is involved in stemness maintenance of glioblastoma, hepatocellular carcinoma, breast cancer, and leukemic SCs." (PMID 37385999, 2023). "In a variety of tumors with different tissue origins, KDM1A has been reported to regulate stemness and drug resistance, such as hepatocellular carcinoma 10, 41, leukemia 42, and breast cancer 43, though the exact mechanisms are diverse." (PMID 35198054, 2022). "Previous studies identified breast development and metastasis pathways of androgen-androgen receptor/KDM1A target genes, and androgen-AR was identified as an oncogenic factor with epigenetic mechanisms involved in breast cancer carcinogenesis." (PMID 33799951, 2021). "The aim of this study was to analyze survival, genetic interaction networks and anticancer immune responses in breast cancer patients with high KDM1A expression and to explore candidate target drugs." (PMID 33799951, 2021). "Using the LN IC50 standard values presented in the GDSC database, we analyzed the drug sensitivity of 50 breast cancer cell lines according to KDM1A expression." (PMID 33799951, 2021). "This candidate drug has the potential to increase breast cancer survival in patients with high KDM1A expression and resistance to chemotherapy." (PMID 33799951, 2021). "Our previous study reported that KDM1A ablation stimulated tumor immunogenicity and increased T cell infiltration in breast cancer." (PMID 34925656, 2021).
breast carcinoma (continued). "We believe that medical oncologists and researchers will be interested in the role of KDM1A in histone methylation and growth of breast cancer and that our results will facilitate further studies." (PMID 33799951, 2021). "Second, our study analyzed the oncogenic role of high KDM1A expression in breast cancer using a bioinformatics approach." (PMID 33799951, 2021). "We identified that alisertib effectively inhibits breast cancer cell lines with high KDM1A expression." (PMID 33799951, 2021). "We identified six anticancer drugs that effectively reduce the growth of breast cancer cells with high KDM1A expression." (PMID 33799951, 2021). "By performing high-throughput drug sensitivity screening using the Genomics of Drug Sensitivity in Cancer (GDSC) database, we also identified new drug candidates for breast cancer with high KDM1A expression." (PMID 33799951, 2021). "We investigated 175 anticancer drugs to which 50 breast cancer cell lines with high KDM1A expression were responsive by using pharmacogenomic screens from the GDSC database." (PMID 33799951, 2021). "This implies that high KDM1A expression results in a worse prognosis in patients with breast cancer." (PMID 33799951, 2021). "Along with in vivo studies, alisertib-based clinical trials in breast cancer patients with high KDM1A expression are needed in the future." (PMID 33799951, 2021). "Although not much is known about the relationship between GATA3 and KDM1B, the paralogous KDM1A(LSD1)’s role in luminal breast cancer via GATA3 is well documented." (PMID 33957863, 2021). "Despite these limitations, our study revealed the functional mechanism of KDM1A in breast cancer through bioinformatics analysis using a large-scale database." (PMID 33799951, 2021). "KDM1A has also been correlated to regulating breast cancer, and studies revealed that inhibiting KDM1A decreases proliferation of breast cancer cells." (PMID 33029224, 2020). "Here, we tested the ability of the clinically proven inhibitor of the lysine-specific demethylase 1 (LSD1/KDM1A) iadademstat (ORY-100) to target SOX2-driven CSC in breast cancer." (PMID 32191225, 2020). "Concomitant drug treatment (a KDM1A inhibitor together with an HDAC inhibitor) is another alternative option, as the inhibition of KDM1A aggravates the cell cycle arrest and apoptosis of breast cancer and glioblastoma cells induced by HDAC inhibitors." (PMID 29921310, 2018). "KDM1A overexpression has been observed in ER− breast cancers as well and was shown to correlate with a reduction in BRCA1 (a familial susceptibility gene for breast cancer) expression." (PMID 29921310, 2018). "Ubiquitin-specific peptidase 28 (USP28) plays a role in the stabilization of KDM1A in multiple cancers, including breast cancer, through its de-ubiquitination." (PMID 29921310, 2018). "The phosphorylation of KDM1A at Ser112 is required for breast cancer metastasis, as the phosphorylated protein inhibits E-cadherin expression." (PMID 29921310, 2018). "The recruitment of estrogen-bound ERα to estrogen-responsive gene promoters is attenuated by the inhibition of KDM1A, and this exerts anti-proliferative effects in breast cancer." (PMID 29921310, 2018). "While the activities of lysine-specific demethylase 1 (LSD1/KDM1A) in facilitating breast cancer progression have been well characterized, the roles of its homolog LSD2 (KDM1B) in breast oncogenesis are relatively less understood." (PMID 29137219, 2017). "Early relapsed prostate carcinomas, sarcomas, and specific types of breast cancer also exhibit high-level KDM1A expression." (PMID 24252778, 2013). "We therefore sought to investigate whether the inhibition of HDAC2, HDAC4, or KDM1A would restore the expression of PHLDA1 in lapatinib-resistant HER2+ breast cancer cells." (PMID 37047202, 2023). "We found that alisertib effectively inhibited breast cancer cell lines with high KDM1A expression." (PMID 33799951, 2021).